APOM (apolipoprotein M)
Diseases named in the same sentence as APOM in open-access papers (continued):
Sharing a sentence is not in itself a finding about the gene and the disease.
heart failure (5 papers, 2020 to 2025). Inability of the heart to pump blood at an adequate rate to meet tissue metabolic requirements. "Apolipoprotein M (ApoM) is associated with lower mortality in heart failure (HF) patients and protects against cardiac and kidney injury in mice." (PMID 40579063, 2025). "In human heart failure (HF) studies, low circulating ApoM levels are associated with increased mortality." (PMID 40579063, 2025). "However, it is important to note that apoM is predominantly transported by HDL, and a recent report has shown that low plasma apoM is independently associated with heart failure." (PMID 38491190, 2024). "Moreover, low plasma ApoM levels are correlated with a risk of death in human heart failure." (PMID 35104242, 2022).
acute myocardial infarction (4 papers, 2016 to 2025). Necrosis of the myocardium, as a result of interruption of the blood supply to the area. "A new SNP C-724del, in the proximal promoter of apoM, was significantly associated with a higher risk for CAD and myocardial infarction, obviously decreased promoter activities and apoM expression in vitro." (PMID 27576735, 2016). "A new single-nucleotide polymorphism (SNP) C-724del in apoM promoter was associated with a higher risk for coronary artery diseases (CAD) and myocardial infarction, could reduce promoter activities and apoM expression in vitro." (PMID 27576735, 2016).
liver cancer (4 papers, 2021 to 2025). An epithelial or non-epithelial malignant neoplasm that arises from the liver. "Experiment in vivo shows that the deletion of ApoM can accelerate the development of mutations in liver cancer cells induced by N-nitrosodiethylamine, a carcinogenic agent." (PMID 36506554, 2022). "WT and ApoM gene-deficient mice were intraperitoneally injected with 35 mg/kg N-nitrosodiethylamine solution to induce liver cancer models." (PMID 34149930, 2021). "Here, we first prove whether ApoM is associated with primary liver cancer." (PMID 34149930, 2021). "Additional studies have revealed the potential value of ApoM in impeding liver-cancer cell metastasis through facilitating ferroptosis." (PMID 39827160, 2025). "ApoM acts as a tumor suppressor and it modulates glycolysis of liver cancer cells via the transcription factor sterol regulatory element-binding protein 1 (SREBP1) pathway." (PMID 36506554, 2022). "Apolipoprotein M is specifically expressed in the liver and participates in liver lipid metabolism, but the evidence that ApoM affects primary liver cancer is insufficient." (PMID 34149930, 2021). "In view of the increasing importance of the liver lipid metabolism environment in malignant liver disease, we initially took the influence of ApoM on liver lipid metabolism as a clue and entry point to explore the correlation between ApoM and liver cancer." (PMID 34149930, 2021). "Further experimental research found that the deletion of ApoM significantly increased the proliferation of mouse liver cancer cells (Hepa1-6) and inhibited the level of apoptosis induced by cisplatin." (PMID 34149930, 2021). "Obviously, in both in vitro and in vivo experiments, ApoM plays a role in inhibiting the occurrence and development of primary liver cancer." (PMID 34149930, 2021). "We constructed a mouse liver cancer cell model with ApoM gene deletion and overexpression and verified it." (PMID 34149930, 2021). "Analyzing 50 matched samples of primary liver cancer in the TCGA database, the expression level of ApoM in cancer tissues was lower than that in paracarcinoma tissues." (PMID 34149930, 2021). "Considering all of these factors, it is reasonable to suspect a connection between ApoM and primary liver cancer." (PMID 34149930, 2021). "The tumor tissue was removed to verify the expression level of ApoM protein, and we thus determined that the expression level of ApoM affected the proliferation of liver cancer cells." (PMID 34149930, 2021). "Liver function ALT and AST levels of liver cancer induction model ApoM-/- group were higher than those of WT group." (PMID 34149930, 2021). "In summary, ApoM plays a role in inhibiting the development of liver cancer cells as shown in proliferation, apoptosis, migration, and invasion related experiments." (PMID 34149930, 2021). "This study systematically explored the role of ApoM in the growth of primary liver cancer cells including the aspects of proliferation, apoptosis, migration, and invasion." (PMID 34149930, 2021). "The expression level of ApoM in the mouse liver cancer cell line was significantly lower than that in the normal liver cell line AML12." (PMID 34149930, 2021). "Accordingly, we concluded that the deletion of the ApoM gene promotes the proliferation of the mouse liver cancer cells Hepa1-6." (PMID 34149930, 2021). "As mentioned, in breast and liver cancer, ApoM can up-regulate the expression of VDR, which may be involved in the anti-neoplastic effect of ApoM." (PMID 36506554, 2022). "In order to explore whether the level of ApoM gene expression affects the level of apoptosis of liver cancer cells, we used flow cytometry to detect the level of apoptosis in the knockout group and overexpression group induced by cisplatin." (PMID 34149930, 2021). "These evidences make us believe that ApoM may be a potential protective factor to inhibit the occurrence and development of primary liver cancer." (PMID 34149930, 2021).
liver cancer (continued). "The results of cell cycle experiments suggested that, in liver cancer cells with ApoM gene deletion, the number of cells in the G0/G1 phase was reduced, and the proportion of cells in the S+G2/M phase was higher; in contrast, upon overexpression of ApoM, the G0/G1 phase was prolonged." (PMID 34149930, 2021). "Is it now appropriate to think about the relationship between ApoM and liver cancer?" (PMID 34149930, 2021). "Edu experiments were used to determine whether the expression level of the ApoM gene affects the proliferation of liver cancer cells." (PMID 34149930, 2021). "Finally, in the liver cancer mouse model, the expression level of ApoM in the cancer tissue was also significantly lower than that in the paracarcinoma tissues." (PMID 34149930, 2021). "In addition, the influences of the ApoM gene on the initiation of liver cancer were aslo examined by observing the rate of tumor formation in vivo model induced by N-nitrosodiethylamine." (PMID 34149930, 2021). "We used N-nitrosodiethylamine to induce primary liver cancer, and observed whether the level of ApoM gene expression affected the occurrence of primary liver cancer." (PMID 34149930, 2021). "Does ApoM also play a role in the development of liver cancer?" (PMID 34149930, 2021). "Therefore, in future work, we will further explore the specific mechanism that enables ApoM to affect the occurrence and development of liver cancer by regulating lipid metabolism." (PMID 34149930, 2021). "Therefore, ApoM may be a potential protective factor to inhibit the occurrence and development of primary liver cancer." (PMID 34149930, 2021). "Therefore, it is important to analyze whether the ApoM gene is involved in the occurrence and development of liver cancer." (PMID 34149930, 2021). "Therefore, ApoM may be a protective factor to prevent primary liver cancer." (PMID 36506554, 2022). "Deficiency of ApoM plays a critical factor in liver steatosis and, in vitro, a lack of ApoM promotes tumour cell survival by blocking liver cancer cells’ apoptosis." (PMID 35158806, 2022). "Unfortunately, we observed that knockout of the ApoM gene increased the migration and invasion capabilities of mouse liver cancer cells, while overexpression did not." (PMID 34149930, 2021). "another 23 clinical specimens of liver cancer were collected for verification, which was consistent with the results of bioinformatics analysis; at the same time, Compared with the normal mouse liver cell line AML12, Hepa1-6 showed a lower ApoM expression level." (PMID 34149930, 2021). "In addition, mouse liver cancer cells lacking ApoM showed stronger migration and invasion capabilities in transwell experiments." (PMID 34149930, 2021). "At the same time, Western blot results showed that, compared to the control group, the ApoM gene deletion group had a higher level of MMP-2 protein expression whereas the overexpression group had a lower level, suggesting that the ApoM gene inhibited the migration and invasion of liver cancer cells." (PMID 34149930, 2021).
rheumatoid arthritis (4 papers, 2013 to 2022). A chronic, systemic autoimmune disorder characterized by inflammation in the synovial membranes and articular surfaces. "APOM rs805297 C/A polymorphism was proved to be associated with increased risk of rheumatoid arthritis in Korean and Chinese populations." (PMID 28476116, 2017). "It was reported that rs805297 SNP affects the levels of apoM mRNA expression in rheumatoid arthritis patients." (PMID 24341666, 2013).
emphysema (3 papers, 2017 to 2024). "APOM is involved in lipid transport and is linked with high-density lipoprotein cholesterol in the pathogenesis of emphysema, which is on the other hand considered as associated with LC." (PMID 28273134, 2017). "Furthermore, APOM plays a key role in lipid transport and is implicated in the pathogenesis of emphysema through its association with HDL cholesterol, which has also been linked to lung cancer." (PMID 39175755, 2024). "Interestingly, higher HDL levels have been associated with lower FEV1/FVC ratio and a higher percentage of emphysema, suggesting a role for the apolipoprotein M/HDL pathway in the pathogenesis of distal airway damage." (PMID 28846677, 2017).
liver disease (3 papers, 2008 to 2022). "Compared to studies on S1P, the studies on the apoM-S1P axis are relatively few, but of interest due to its emerging importance in inflammatory diseases, in particular its role in hepatic diseases and HCC." (PMID 35158806, 2022). "Plasma proteome profiling of 48 patients with and without cirrhosis or NAFLD revealed six statistically significantly changing proteins (ALDOB, APOM, LGALS3BP, PIGR, VTN, and AFM), two of which are already linked to liver disease." (PMID 30824564, 2019). "In the present study we examined plasma levels of lipids, lipoproteins, apoAI, apoB and apoM in the HCC patients compared with the other liver diseases and normal subjects." (PMID 18652652, 2008). "As apoM is exclusively expressed in hepatocytes and kidney tubular cells, the plasma apoM levels may also be changed in the HCC patients and in other liver diseases." (PMID 18652652, 2008).
nephritis (3 papers, 2019 to 2021). Inflammation of renal tissue. "Also, the apoM serum level < 24.81 mg/L was an independent predictive factor for lgAVN and can be independently associated with the presence of nephritis in lgAV patients." (PMID 31885732, 2019). "Besides, the apoM serum level < 24.81 mg/L was an independent predictive factor for lgAVN and can be independently associated with the presence of nephritis in lgAV patients." (PMID 31885732, 2019). "ApoM (OR = 0.32, 95%CI = 0.12‐0.85, p = 0.023) was identified as a protective factor for nephritis in all lgAV patients." (PMID 31885732, 2019). "Patients with concurrent nephritis and rash (n = 8) had significantly lower apoM levels compared to patients with concurrent arthritis and rash (n = 7), p = 0.01." (PMID 31046824, 2019). "Meanwhile, in multivariate analysis, apoM was the independent predictor of the presence of nephritis in lgAV patients." (PMID 31885732, 2019). "Patients with IgAV-induced nephritis have increased apoM and S1P levels compared to healthy controls but lower levels than those without nephritis." (PMID 34722589, 2021). "Serum apoM levels in lgAVN patients were lower than lgAV without nephritis patients." (PMID 31885732, 2019). "ApoM, meanwhile, was lower in patients with nephritis than in those without nephritis." (PMID 31885732, 2019).
Nephropathy (3 papers, 2020 to 2025). A nonspecific term referring to disease or damage of the kidneys. "In animal studies, ApoM protects against kidney disease in mice by attenuating kidney fibrosis and injury and suppressing nephropathy." (PMID 40579063, 2025). "Surprisingly, the apoM levels were higher in patients with nephropathy and T2D." (PMID 34093440, 2021).
non-small cell lung carcinoma (3 papers, 2020 to 2022). A group of at least three distinct histological types of lung cancer, including non-small cell squamous cell carcinoma, adenocarcinoma, and large cell carcinoma. "In 2018, our research demonstrated that APOM can promote the proliferation and invasion of non-small cell lung cancer cells, which is related to the upregulation of S1P-receptor 1 and activation of the ERK1/2 and PI3K/AKT signalling pathways induced by APOM12." (PMID 33173129, 2020).
Stroke (3 papers, 2020 to 2024). Sudden impairment of blood flow to a part of the brain due to occlusion or rupture of an artery to the brain. "Particularly, the increase in ApoE and ApoM 24 and 96 h post-stroke has been related to a worse three-month recovery score, as assessed by the NIHSS score." (PMID 38732018, 2024). "Of note, administration of engineered ApoM with long plasma half-life has resulted into increased plasma concentration of S1P and cardiac protection with recovery from stroke in experimental mice." (PMID 32923406, 2020).
systemic inflammatory response syndrome (3 papers, 2012 to 2024). SIRS is a serious condition related to systemic inflammation, organ dysfunction, and organ failure. "It was observed that in patients with septic shock and systemic inflammatory response syndromes apoM concentration significantly decrease and is reversely correlated to acute phase markers." (PMID 28376720, 2017).
acute kidney injury (2 papers, 2021 to 2024). Sudden and sustained deterioration of the kidney function characterized by decreased glomerular filtration rate, increased serum creatinine or oliguria. "This prompted the suggestion of kidney derived apoM as an important modulator of acute kidney injury." (PMID 38313311, 2024). "A recent publication suggest that the detrimental effects of IL-1 signaling during acute kidney injury are mediated via suppression of apoM expression in proximal tubular epithelial cells highlighting the possible important role of apoM in kidney functionality." (PMID 38313311, 2024). "Therefore, the purpose of this study was to generate a novel kidney-specific apoM transgenic mouse and subsequently to determine if kidney-derived apoM contributes to the plasma pool of apoM as well as its role in acute kidney injury." (PMID 38313311, 2024). "The effect of apoM on acute kidney injury was in addition assessed in a model of I/R injury." (PMID 38313311, 2024). "The aim of this study was to address the role of apoM in kidney biology and in acute kidney injury." (PMID 38313311, 2024). "Similar, our observations in apoM-KO mice support that a change in apoM levels does not affect inflammatory markers after I/R induced acute kidney injury." (PMID 38313311, 2024). "Finally, we show that overexpression of apoM locally in the kidney is not able to protect against either cisplatin or I/R induced acute kidney injury." (PMID 38313311, 2024). "However, overexpression of human apoM in the kidney did not protect against acute kidney injury." (PMID 38313311, 2024).
Arthritis (2 papers, 2019 to 2024). Inflammation of a joint. "Mice deficient in ApoM, the chaperone on HDL that delivers S1P to S1PR1 and has particularly effective antiinflammatory effects, show amplified arthritis in response to SIA." (PMID 38855867, 2024).
breast carcinoma (2 papers, 2023). "APOM carries and stabilizes the level of sphingosine-1-phosphate, a molecule responsible for reducing cancer invasion, thus suggesting the underlying mechanism underpinning APOM-reduced breast cancer growth." (PMID 38067270, 2023). "A recent study illustrated that APOM expression is statistically significantly lower in breast cancer tissue as compared to normal tissue." (PMID 38067270, 2023). "In vitro data also showed APOM to suppress breast cancer cell proliferation, migration, and invasion." (PMID 38067270, 2023).
chronic obstructive pulmonary disease (2 papers, 2016 to 2019). A chronic and progressive lung disorder characterized by the loss of elasticity of the bronchial tree and the air sacs, destruction of the air sacs wall, thickening of the bronchial wall, and mucous accumulation in the bronchial tree. "Recently, variations in a component of high-density lipoprotein (HDL), namely apolipoprotein M (apoM), were found to be associated with chronic obstructive pulmonary disease (COPD)." (PMID 27001252, 2016).
Cirrhosis (2 papers, 2008 to 2019). A chronic disorder of the liver in which liver tissue becomes scarred and is partially replaced by regenerative nodules and fibrotic tissue resulting in loss of liver function. "ApoM levels were even higher in the patients suffered from chronic hepatitis and cirrhosis, the later with highest plasma apoM levels." (PMID 18652652, 2008). "However, plasma apoM levels in HCC patients were significantly increased than those in the normal subjects, but lower than those in the chronic hepatitis and cirrhosis patients." (PMID 18652652, 2008).
colon cancer (2 papers, 2019 to 2020). "Apolipoprotein M mRNA has however been closely associated with nodal metastasis in colon cancer." (PMID 31042781, 2019).
dyslipidaemia (2 papers, 2013 to 2022). "The polymorphisms in the ApoM gene have been associated with the risk of dyslipidaemia in RA patients." (PMID 35330214, 2022).
gestational hypertension (2 papers, 2025). "Apolipoprotein M (APOM) has been reported to be a diagnostic marker for preeclampsia, whereas serum peptides derived from kininogen-1 (KNG1) were part of a panel able to differentially diagnose preeclamptic pregnancies." (PMID 40974471, 2025). "Further supporting the importance of PON1, it was supported that impaired HDL cholesterol efflux and PON1 activity in cord blood, along with increased maternal PON1 and apoM levels early in pregnancy, are associated with the risk of gestational hypertension." (PMID 39857440, 2025).
glomerular disease (2 papers, 2023 to 2024). "Moreover, it should be noted that a number of new potential markers that could be used to distinguish between severe glomerulopathies—such as APOM, ITOH2, and LUM—were identified." (PMID 37110557, 2023).